ABCC8 (ATP binding cassette subfamily C member 8)
Diseases named in the same sentence as ABCC8 in open-access papers (continued):
Sharing a sentence is not in itself a finding about the gene and the disease.
epilepsy (10 papers, 2013 to 2026). A brain disorder characterized by episodes of abnormally increased neuronal discharge resulting in transient episodes of sensory or motor neurological dysfunction, or psychic dysfunction. "Similar cases of PNDM with neurological sequelae have been reported, particularly in KCNJ11 or ABCC8 mutations, where epilepsy may arise from direct channelopathy effects." (PMID 41393705, 2025). "Gain of channel function (GOF) mutations in the genes encoding Kir6.2 (KCNJ11) or the associated regulatory ssulfonylurea receptor 1 subunit (ABCC8), cause developmental delay, epilepsy and neonatal diabetes (DEND) due to suppressed cell excitability in pancreatic β-cells and neurons." (PMID 23667671, 2013). "Approximately 25% of patients with a mutation of the ABCC8 or KCNJ11 genes have neurological disorders ranging from psychomotor disorders to delayed cognitive development associated with severe epilepsy (DEND syndrome: Developmental delay, Epilepsy, and Neonatal Diabetes)." (PMID 33102403, 2020). "Indeed, despite a single case report of an individual with ABCC8-MODY and epilepsy, numerous studies have reported the absence of neurological defects among different ABCC8-MODY cohorts." (PMID 38980630, 2024).
Obesity (10 papers, 2017 to 2025). Accumulation of substantial excess body fat. "Heterozygous ABCC8 mutations were found in three patients with obesity-associated insulin secretion disorder." (PMID 38550917, 2024). "Since insulin has diverse functions in the body regulating carbohydrates and lipids by stimulating lipid synthesis from glucose and prevents lipid degradation or lipolysis, we evaluated the relationship between the ABCC8 C/T polymorphism with obesity, cholesterol, triglyceride and lipoproteins." (PMID 29751826, 2018). "Co-localization analysis suggested that LPL (as a TG-lowering drug target), CETP (as an HDL-raising drug target), ABCC8 (as a glucose-lowering drug target) and GIPR (as an anti-obesity drug target) were unlikely to share a causal variant with LS." (PMID 39661645, 2025).
developmental delay (9 papers, 2013 to 2024). "Of the patients carrying KCNJ11 and ABCC8 mutations, there was developmental delay in one patient diagnosed as iDEND, including one with congenital cataract." (PMID 26839896, 2016).
Glucose intolerance (9 papers, 2012 to 2024). Glucose intolerance (GI) can be defined as dysglycemia that comprises both prediabetes and diabetes. "Besides, insulin content and gene expression decreased and led to the disruption of insulin secretion and glucose intolerance in the mouse model with an inactivating variant of ABCC8." (PMID 34631896, 2021). "Huopio and Laakso first described evidence of mild glucose intolerance in KATP‐HI, based on responses to oral glucose in families with the Finnish ABCC8 founder mutation for dominantly inherited congenital HI." (PMID 31464105, 2019).
subarachnoid hemorrhage (8 papers, 2015 to 2024). A serious neurological disorder characterized by intracranial hemorrhage into the subarachnoid space. "A reduction in the expression of pro-inflammatory cytokines in models of subarachnoid hemorrhage and experimental autoimmune encephalomyelitis was associated with both pharmacological inhibition of Abcc8 or Abcc8 gene suppression." (PMID 36681815, 2023). "In models of subarachnoid hemorrhage and multiple sclerosis, gene suppression or pharmacological inhibition (glibenclamide) of Abcc8/Sur1 significantly ameliorates neuroinflammation and improves neurological function, with these effects attributed to inhibition of Sur1-Trpm4 channels." (PMID 27246103, 2016).
breast carcinoma (7 papers, 2013 to 2026). "In another breast-cancer study, high expression of ABCC1 and low expression of ABCC8 were found to be more strongly associated with high-grade breast cancer than with the less-aggressive grades I and II51." (PMID 32587767, 2020). "High expression of ABCC1 and low expression of ABCC8 are correlated with the aggressiveness of breast cancer." (PMID 34650973, 2021). "We tested the role of the ABCC8/Sur1, ABCC9/Sur2A/B, KCNJ11/Kir6.2, and KCNJ8/Kir6.1 genes experimentally in a minoxidil-induced renal tumor in male rats and in the female canine breast cancer, a spontaneous animal model of disease, and in the pharmacovigilance and omics databases." (PMID 37180726, 2023).
transient neonatal diabetes mellitus (7 papers, 2020 to 2026). Transient neonatal diabetes mellitus (TNDM) is a genetically heterogeneous form of neonatal diabetes (NDM) characterized by hyperglycemia presenting in the neonatal period that remits during infancy but recurs in later life in most patients. "Conversely, ABCC8 mutations are more commonly linked to transient neonatal diabetes mellitus (TNDM), although they also account for a significant proportion of permanent cases." (PMID 41614934, 2026). "ABCC8 is another rare MODY-related gene variant with a 17% proportion in our study, which was also reported to be associated with permanent or transient neonatal diabetes mellitus and the opposite phenotype, hyperinsulinaemic hypoglycaemia." (PMID 40303944, 2025). "Other pathogenic ABCC8 variants are associated with autosomal dominant type 2 diabetes mellitus (OMIM 125853), PNDM (OMIM 606176) and transient neonatal diabetes mellitus (TNDM) (OMIM 610374)." (PMID 38791571, 2024).
Beckwith-Wiedemann syndrome (6 papers, 2022 to 2025). Beckwith-Wiedemann syndrome (BWS) is a genetic disorder characterized by overgrowth, tumor predisposition and congenital malformations. "In some cases, paternal isodisomy of chromosome 11p15 occurs in multiple tissues, causing Beckwith-Wiedemann Syndrome spectrum (BWSp); severe diazoxide-unresponsive HI can occur in BWSp due to 11pUPD when there is a concurrent paternally inherited ABCC8 or KCNJ11 disease-causing variant." (PMID 37454648, 2024). "The chromosomal region 11p15, which harbors the ABCC8 and KCNJ11 genes, is also involved in several rare genetic syndromes associated with CHI, most notably Beckwith-Wiedemann syndrome (BWS)." (PMID 40904956, 2025). "ABCC8 and KCNJ11 are neighboring genes and they are located on the short arm of chromosome 11 in region 11p15 proximal to the imprinting region that when disrupted causes imprinting disorders Beckwith-Wiedemann syndrome (BWS) and Russell-Silver syndrome (RSS)." (PMID 36339418, 2022). "Genetic studies were negative for mutations in ABCC8, KCNJ11, GCK, or GLUD1 genes, multiple endocrine neoplasia (MEN) type 1, and Beckwith-Wiedemann syndrome." (PMID 39170749, 2024).
experimental autoimmune encephalomyelitis (6 papers, 2015 to 2023). An autoimmune demyelinating disease of the central nervous system that is produced experimentally in animals by the injection of homogenized brain or spinal cord in Freund's adjuvant. "ATP-binding cassette transporter sub-family C member (ABCC) 8 encodes for sulfonylurea receptor 1 (Sur1) and silencing of Abcc8 or inhibition of Sur1-Trpm4 attenuate inflammation and disease progression in experimental autoimmune encephalomyelitis." (PMID 35203642, 2022). "The expression of pro-inflammatory cytokines (TNFα, IFNγ and IL-17) in models of SAH and experimental autoimmune encephalomyelitis (EAE) is decreased with both pharmacological inhibition of SUR1 or Abcc8 gene suppression." (PMID 34769328, 2021). "Similarly, in a murine model of experimental autoimmune encephalomyelitis, silencing of Abcc8 or of Trpm4 results in the same phenotype, with reduced neuroinflammation and preservation of white matter." (PMID 27246103, 2016).
type 1 diabetes (6 papers, 2010 to 2025). "One out of 24 had a mutation in ABCC8, suggesting that screening of ABCC8 should be considered in patients with AAB negative type 1 diabetes." (PMID 20863361, 2010).
DEND syndrome (5 papers, 2013 to 2024). DEND syndrome is a very rare, generally severe form of neonatal diabetes mellitus (NDM) characterized by a triad of developmental delay, epilepsy, and neonatal diabetes. "Numerous gain-of-function mutations have been identified in the genes encoding Kir6.2 (KCNJ11) or the associated regulatory SUR1 subunit (ABCC8) of patients affected by DEND syndrome." (PMID 24062639, 2013).
Impaired glucose tolerance (5 papers, 2019 to 2022). An abnormal resistance to glucose, i.e., a reduction in the ability to maintain glucose levels in the blood stream within normal limits following oral or intravenous administration of glucose. "In presence of family history of HY and/or Impaired Glucose Tolerance, Impaired Fasting Glucose or GDM, the hypothesis of ABCC8/KCNJ11, HNF1A or HNF4A gene mutations can be formulated." (PMID 32928245, 2020).
pancreatic cancer (5 papers, 2017 to 2024). "Sulfonylureas and glinides blocking the pancreatic Kir6.2-Sur1 subunits showed a higher risk for pancreatic cancer in line with the positive prognostic role of the ABCC8 gene but low risks for common cancers." (PMID 37180726, 2023). "Three out of them (ABCC2, ABCC5, ABCC8) have been already described for their association with drug resistance in pancreatic cancer." (PMID 29285254, 2017). "ABCC8/KCNJ11 were observed sharing gene regions with pancreatic cancer risk (PP4 = 0.836)." (PMID 38504335, 2024). "Although this ABCC8 gene mutation could be incidental, there could be a relationship between this mutation, pancreatic malformation, chronic pancreatitis and pancreatic neoplasm." (PMID 33728157, 2021). "In SMR analyses, ABCC8/KCNJ11, DPP4, PPARG, ETFDH, and PRKAB1 were associated with anal carcinoma, cardia cancer, and pancreatic cancer." (PMID 38504335, 2024). "This was in harmony with our study where ABCC8/KCNJ11 was correlated with a higher risk of ICC and pancreatic cancer, as well as a lower risk of anal carcinoma and HCC." (PMID 38504335, 2024). "Associations of ABCC8/KCNJ11, DPP4, GLP1R, GPD2, PPARG, PRKAB1, and SLC5A2 with anal carcinoma, cardia cancer, gastric cancer, HCC, ICC, pancreatic cancer, and rectum cancer were revealed in two-sample MR analyses." (PMID 38504335, 2024). "In addition, the mediation effect of BMI on the causal connection between ABCC8/KCNJ11 and pancreatic cancer risk was detected." (PMID 38504335, 2024). "Furthermore, ABCC8/KCNJ11, DPP4, GLP1R, PRKAB1, and GPD2 shared causal variants within anal cancer, HCC, ICC, pancreatic cancer, and rectum cancer according to the colocalization analyses." (PMID 38504335, 2024). "The promoting effect of ABCC8/KCNJ11 on pancreatic cancer was also observed in SMR analysis." (PMID 38504335, 2024). "Moreover, ABCC8 (OR = 1.142; 95% CI: 1.013–1.287; P-value = 0.030), ETFDH (OR = 1.249; 95% CI: 1.006–1.550; P-value = 0.044), and PRKAB1 (OR = 0.798; 95% CI: 0.662–0.962; P-value = 0.018) were associated with pancreatic cancer risks." (PMID 38504335, 2024). "The mediation effect of body mass index (OR: 0.938; 95% CI: 0.884–0.995; proportion of mediation effect: 3.001%; P-value = 0.033) on ABCC8/KCNJ11 and pancreatic cancer was uncovered." (PMID 38504335, 2024). "Simultaneously, the colocalization analyses revealed that ABCC8/KCNJ11 shared identical genetic regions with anal carcinoma, HCC, ICC, and pancreatic cancer." (PMID 38504335, 2024). "Furthermore, BMI played a mediation role in the correlation between ABCC8/KCNJ11 and pancreatic cancer via the mediation MR analyses." (PMID 38504335, 2024).
pulmonary arterial hypertension (5 papers, 2020 to 2025). "Mutation in the ATP Binding Cassette Subfamily C Member 8 (ABCC8) gene is associated with pulmonary arterial hypertension." (PMID 32850550, 2020). "Moreover, an ABCC8 mutation was detected in one patient with pulmonary arterial hypertension." (PMID 38212772, 2024).
Cantu syndrome (4 papers, 2018 to 2024). "The gain of function (GOF) mutations of the ABCC8 and KCNJ8 subunits is associated with Cantu syndrome, which is characterized by cardiovascular phenotypes in human and animals, and cases of pituitary adenoma in some families." (PMID 39200356, 2024).
familial hyperinsulinemic hypoglycemia (4 papers, 2010 to 2025). "KMT2D-related Kabuki syndrome 1 (OMIM: 147920) and ABCC8-related familial hyperinsulinemic hypoglycemia (OMIM 256450) were two of the most common disorders." (PMID 33240318, 2020). "In a patient with congenital hyperinsulinism, a previously undescribed variant c.4454A>C (HG38, chr11:17394357T>G, coverage depth 256×) in exon 37 of the ABCC8 gene was identified in a homozygous or hemizygous state, resulting in an amino acid substitution p.(Gln1485Pro)." (PMID 39859454, 2025).
gestational diabetes (4 papers, 2012 to 2024). Carbohydrate intolerance first diagnosed during pregnancy. "The clinical history of our patient resembles that of individuals with the ABCC8-E1506K mutation, several of whom had gestational diabetes that remitted after pregnancy but subsequently returned." (PMID 38366195, 2024).
hemorrhagic stroke (4 papers, 2013 to 2023). A stroke caused by a bleed on the brain. "As noted, we did not observe differences in RNA expression of Abcc8 or Trpm4, which code for the Sur1-Trpm4 channel, despite previous ischemic and hemorrhagic stroke studies reporting this." (PMID 34081746, 2021).
intracranial hypertension (4 papers, 2020 to 2021). A finding characterized by increased cerebrospinal fluid pressure within the skull. "A significant interaction effect has been reported between rs8104571 and three of the significant ABCC8 SNPs, all located in intron-10 (rs2237982, rs2293261, rs11024286), that influences intracranial hypertension." (PMID 31936452, 2020). "Interestingly, significant interactions between ABCC8 and TRPM4 single nucleotide polymorphisms (SNPs) have also been reported, where certain genotype combinations containing risk alleles in both genes markedly and consistently increase the odds of several measures of intracranial hypertension." (PMID 34769328, 2021). "They support the theory that ABCC8 and TRPM4 genetic variation may play a role in cerebral edema development, intracranial hypertension and outcome after TBI." (PMID 31936452, 2020).
metabolic syndrome (4 papers, 2015 to 2024). A cluster of metabolic risk factors for CARDIOVASCULAR DISEASES and TYPE 2 DIABETES MELLITUS. "Recently, it has been shown that polymorphisms in ABCA1 and ABCC8 may be associated with metabolic syndrome." (PMID 26788366, 2015). "Dyslipidemia and hypertension were most common in HNF1B‐MODY (52.9% dyslipidemia, 58.3% hypertension) and KLF11‐MODY (75% dyslipidemia, 100% hypertension), while were less common in ABCC8‐MODY (18.2% dyslipidemia, 25.0% hypertension)." (PMID 39511990, 2024).
Usher syndrome (4 papers, 2015 to 2025). A syndromic diseae characterized by the association of sensorineural deafness (usually congenital) with retinitis pigmentosa and progressive vision loss. "CHI in this condition is similar in its clinical presentation and pathophysiology to the ABCC8-deficient autosomal recessive diffuse form, while the remainder of the phenotype represents Usher syndrome type 1C and is explained by the USH1C defect." (PMID 37065762, 2023). "Some studies report PHHI associated with Usher syndrome, as genes responsible for normal ear and eye development are located adjacent to the loci of ABCC8 and KCNJ11." (PMID 25871929, 2015). "From a clinical point of view, three patients have clinical findings suggestive of deafness, which has been previously reported in the literature, where deletions in the ABCC8 gene also cause deletions in an adjacent gene USH1C associated with hearing loss (Usher syndrome)." (PMID 25871929, 2015). "SNP array analysis of all 8 individuals in the solved cohort with a deletion of ABCC8 exons 1-22, demonstrated the deletion extended over exons 1-19 of the adjacent USH1C gene, confirming a diagnosis of Usher syndrome type 1c." (PMID 40041288, 2025).
brain tumors (3 papers, 2020 to 2024). "At present, the expression and function of ABCC8 mRNA in brain tumors is less studied." (PMID 32728190, 2020). ".It is suggested that ABCC8 expression is lower in malignant brain tumors." (PMID 32728190, 2020).
diabetic ketoacidosis (3 papers, 2017 to 2021). The metabolic condition resulted from uncontrolled diabetes mellitus, in which the shift of acid-base status of the body toward the acid side because of loss of base or retention of acids other than carbonic acid is accompanied by the accumulation of ketone bodies in body tissues and fluids. "We report a case of a 9-week-old presenting in diabetic ketoacidosis and later diagnosed with an activating ABCC8 mutation who is in the process of transitioning from insulin therapy to sulfonylurea." (PMID 28540314, 2017). "Case 1 (male, 18 years, compound heterozygous ABCC8 mutation) and case 2 (female, 29 years, heterozygous KCNJ11 mutation) presented with severe diabetic ketoacidosis at 6 and 16 weeks of age." (PMID 28173619, 2017).
gastric cancer (3 papers, 2023 to 2024). A primary or metastatic malignant neoplasm involving the stomach. "Upregulation of ABCC8 was also found in brain tumors and gastric cancer and downregulation in colon–rectal cancer (CRC)." (PMID 37180726, 2023).
glioblastoma (3 papers, 2020 to 2021). The most malignant astrocytic tumor (WHO grade IV). "The expression of ABCC8 was higher in supratentorial ependymoma than in glioblastoma and metastasis (P < 0.05), and higher in medulloblastoma than in glioblastoma." (PMID 32728190, 2020). "The results showed that the percentage of cells expressing ABCC8 in total tissue area (mean ± SD) was 3.9 ± 4 in glioblastoma, 4.1 ± 3.1 in brain metastasis, 8.2 ± 7.2 in medulloblastoma, 9.1 ± 7 in supratentorial ependymoma, and 8.1 ± 5.9 in the posterior cranial cavity." (PMID 32728190, 2020).
hemorrhage (3 papers, 2015 to 2021). Loss of blood from the vascular compartment to the exterior or into nonvascular body space as a result of rupture or severance of the blood vessels. "For example, ABCC8 eQTLs associated with increased brain-specific ABCC8 mRNA levels were also associated with increased odds of hemorrhage progression." (PMID 34769328, 2021). "This genetic association study examines the association of DNA sequence variability in ABCC8 and TRPM4 with intraparenchymal hemorrhage progression in patients with severe traumatic brain injury (TBI)." (PMID 34309670, 2021). "Intraparenchymal hemorrhage progression models containing clinical covariates were outperformed by adding significant ABCC8 and TRPM4 genotypes." (PMID 34309670, 2021).
) channelopathies (2 papers, 2022 to 2026). "Outside of the TGFβ/BMP pathway, channelopathy gene, ABCC8, is one of the most common causes of PAH, accounting for ~1% of cases." (PMID 35204766, 2022). "Roles of genetic variants in three channelopathy genes—ABCC8, ATP13A3, and KCNK3—have been validated in multiple independent studies, and explain ~2.7% of PAH cases." (PMID 35204766, 2022).
atrial fibrillation (2 papers, 2012 to 2025). A disorder characterized by an electrocardiographic finding of a supraventricular arrhythmia characterized by the replacement of consistent P waves by rapid oscillations or fibrillatory waves that vary in size, shape and timing and are accompanied by an irregular ventricular response. "Mendelian randomization analyses suggest that genetic proxies for antidiabetic drug targets—KCNJ11/ABCC8, SLC5A2, and RXRB—reduce the risk of paroxysmal tachycardia (PT), right bundle branch block (RBBB), and atrial fibrillation (AF), respectively." (PMID 41357784, 2025).
diabetic kidney disease (2 papers, 2019 to 2021). Progressive kidney disorder caused by vascular damage to the glomerular capillaries, in patients with diabetes mellitus. "Further studies are also required to confirm the risk and the precise diabetic kidney disease mechanism of ABCC8 variants." (PMID 34631896, 2021).